KRTAP3-3 (keratin associated protein 3-3)
Description:
In the hair cortex, hair keratin intermediate filaments are embedded in an interfilamentous matrix, consisting of hair keratin-associated proteins (KRTAP), which are essential for the formation of a rigid and resistant hair shaft through their extensive disulfide bond cross-linking with abundant cysteine residues of hair keratins. The matrix proteins include the high-sulfur and high-glycine-tyrosine keratins.
Synonyms: KAP3.3; KRTAP3.3
Tractability: No criterion of Open Targets' tractability assessment is met for any kind of drug.
Gene: Protein-coding gene on chromosome 17 (40,993,430 to 40,994,164, reverse strand). Ensembl gene ENSG00000212899.
Pathways (Reactome):
Developmental Biology: Keratinization
Gene Ontology:
Molecular function: protein binding; structural molecule activity
Cellular component: cytosol; keratin filament
Genetic constraint (gnomAD): Loss-of-function variants: 10 observed, 6.69 expected, observed/expected ratio (o/e) 1.49, 90% interval 0.88 to 1.93. That is too few expected variants to judge how well the gene tolerates losing a copy. Missense variants: 98 observed, 116.01 expected, observed/expected ratio (o/e) 0.84, 90% interval 0.72 to 1. Synonymous variants: 49 observed, 46.34 expected, observed/expected ratio (o/e) 1.06, 90% interval 0.84 to 1.34.
Homologues: Orthologues: chimpanzee KRTAP3-3 (100% identical), mouse Krtap3-2 (85% identical), mouse Krtap3-3 (85% identical), rat Krtap3-2 (85% identical), rat Krtap3-3 (85% identical). Paralogues in human: KRTAP3-2 (98% identical), KRTAP3-1 (72% identical), KRTAP24-1 (38% identical).